METTL3 (methyltransferase 3, N6-adenosine-methyltransferase complex catalytic subunit)
Diseases named in the same sentence as METTL3 in open-access papers (continued):
Sharing a sentence is not in itself a finding about the gene and the disease.
tumor (continued). "In addition, METTL3 expression was significantly increased in OC tissues compared with other tumour tissues." (PMID 40356909, 2025). "METTL3, one of the methyltransferases responsible for m6A methylation, has been shown to potentially contribute to cancer radioresistance by improving DNA repair capacity in malignant cells, promoting CSCs generation, and inducing tumor cell autophagy." (PMID 40823093, 2025). "Despite higher METTL3 expression being significantly associated with lower tumour grade, ER and PR positivity, and non-TNBC status, METTL3 expression did not correlate with survival outcomes in our patient cohort, when considering the cohort as a whole." (PMID 41310336, 2025). "The upregulation of METTL3 significantly facilitated OS tumor growth in nude mice." (PMID 40510136, 2025). "Xenograft tumor models indicated that METTL3 promoted NPC growth in vivo." (PMID 39990661, 2025). "For example, METTL3‐mediated mRNA modifications may enhance the translation of oncogenic factors while simultaneously repressing tumour suppressor genes." (PMID 40052548, 2025). "Previous studies mainly focused on the role of METTL3 in mediating mRNA metabolism and tumor progression through its target gene m6A methylation regulation, however, the limited understanding of METTL3-specific functional regulation, especially in post-translational modification, still exists." (PMID 40495163, 2025). "Notably, METTL3 expression was also studied in paraffin-embedded sections of human HCC and normal liver specimens using immunohistochemistry (IHC), and the results indicated high expression of METTL3 in tumor tissues." (PMID 39799112, 2025). "Our findings suggest that targeting the piR-31115/METTL3/YAP1/IGF2BP2 signalling pathway may offer a promising strategy for inhibiting tumour angiogenesis in TNBC." (PMID 39820521, 2025). "Moreover, we evaluated the tumor burden through microscopic analysis with H&E staining and found that Mettl3 cKO mice had a substantially greater number of tumors and larger relative tumor areas compared with the control group." (PMID 40103332, 2025). "Whether miR-101 functions as a tumor suppressor via METTL3 and regulate the expression of METTL3 requires further investigation." (PMID 41390674, 2025). "Investigating the interplay between METTL3 expression and the presence of various immune cell types could yield insights into the potential for combination therapies that harness both direct tumour targeting and immunomodulatory approaches." (PMID 40052548, 2025). "METTL3 promotes tumor proliferation in bladder cancer via m6a." (PMID 41211186, 2025). "In addition, the expression of metastasis-related markers matrix metallopeptidase 2 (MMP2), MMP9, and intercellular cell adhesion molecule-1 (ICAM1) was decreased, suggesting that METTL3 overexpression suppressed transcription of key tumor metastasis genes." (PMID 41208889, 2025). "Thus, METTL3 can have tumor-suppressive effects in certain cellular contexts by modulating metastasis-relevant genes." (PMID 41301491, 2025). "In response to viral mimicry, METTL3-mediated m6A on RIG-I transcripts modulates innate antiviral signaling and may influence tumor-associated inflammation." (PMID 41280938, 2025). "Myeloid-specific ablation of Mettl3 increased tumor growth and metastasis and weakened the efficacy of anti-PD-1 therapy, in part by skewing macrophage polarization and altering inflammatory signaling, linking m6A to macrophage programming that shapes T-cell responses." (PMID 41280938, 2025). "Additionally, analysis of publicly available GEO datasets (GSE114564) confirmed the upregulation of METTL3 in advanced HCC tumor tissues compared with healthy human livers and early HCC tissues." (PMID 40103332, 2025). "METTL3-mediated m6A RNA methylation promotes anti-tumor immunity in natural killer cells." (PMID 40529813, 2025).
tumor (continued). "Additionally, tumour microenvironment lactate induces METTL3 upregulation in myeloid‐derived macrophages through histone lactylation, which drives the immunosuppressive function of tumour‐infiltrating myeloid cells." (PMID 41020792, 2025). "METTL3, the ‘writer’ of m6A, plays a role in tumor cell development in an m6A-dependent manner." (PMID 40097750, 2025). "Importantly, context-dependent tumor-suppressive effects of METTL3 have also been reported, reflecting cell type, isoform, and microenvironmental dependencies." (PMID 41515964, 2025). "TcircMVP regulates the anti-tumor immune function of β-catenin by enhancing METTL3." (PMID 39744434, 2025). "Moreover, research has shown that miR-186 regulates the proliferation and invasion capabilities of tumor cells by inhibiting N6-methyladenosine (m6A) methyltransferase-like 3 (METTL3), thereby affecting the Wnt/β-catenin signaling pathway." (PMID 41393242, 2025). "Importantly, inhibition of METTL3 through the use of STM2457 was found to reduce tumor burden and promote apoptosis." (PMID 39902961, 2025). "In parallel, tumor-conditioned myeloid cells undergo epitranscriptomic reprogramming: lactate accumulation in the TME induces METTL3 via protein lactylation, which enhances m6A-JAK1–STAT3 signaling in tumor-infiltrating myeloid cells and reinforces immunosuppressive transcriptional programs." (PMID 41280938, 2025). "In addition, the number of PCNA-/METTL3-/TRIB3-positive cells was higher in tumor samples from the Tan-IIA treatment group." (PMID 39910904, 2025). "Last, the tumor‐promoting effect of the METTL3/HDAC6 axis was verified with clinical data." (PMID 39535388, 2025). "Overexpression of METTL3 notably promoted OS tumor growth in mice." (PMID 40510136, 2025). "Therefore, addressing context-dependent METTL3 functions (e.g., tumor stage-specific roles) and resistance mechanisms will be critical to translating these insights into precision therapies." (PMID 40313614, 2025). "METTL3 plays a significant role in regulating tumor mRNAs within ccRCC." (PMID 40313614, 2025). "Indeed, the decay rate of Smad3 mRNA was significant increased from 0.97 hours to 3.04 hours in tumor MO-MDSC after Mettl3 knockdown." (PMID 41360769, 2025). "Consequently, immunohistochemistry (IHC) analysis showed HDAC6 and Ki67 levels were significantly elevated, while acetylated α‐tubulin levels were significantly reduced in xenograft tumor tissues overexpressing METTL3." (PMID 39535388, 2025). "Moreover, the acceleration of apoptosis in tumor cells, specifically HepG2 cells, can be achieved by silencing METTL3 expression." (PMID 40136363, 2025). "Consistent with the pattern in HCC patients, IHC staining and western blot both showed a dramatic increase in METTL3 protein in liver tissues from tumor‐inducing mice relative to those from controls, with higher levels in tumor regions than in adjacent nontumor regions." (PMID 40103332, 2025). "Furthermore, immunohistochemistry and Western blot analyses confirmed a significant upregulation of METTL3 expression in tumor tissues compared to normal tissues." (PMID 40495163, 2025). "For example, extracellular acidosis suppressed a METTL3–m6A–ITGB1 axis in tumor cells to reduce CD8+ infiltration; restoring the axis increased T-cell entry and tumor control, illustrating how tissue pH can indirectly govern T-cell access through epitranscriptomic wiring." (PMID 41280938, 2025). "Furthermore, a phase I study (NCT06762925) on the efficacy and mechanism of METTL3 peptide inhibitors in enhancing anti-tumor immune response in patients with urological tumors is conducting." (PMID 41373022, 2025). "Chi-square analysis showed that METTL3 expression was significantly associated with tumor size and hepatitis B surface antigen (HBsAg) status, but not with gender, age, hepatitis C core antigen (HCVAg), or tumor-node-metastasis (TNM) stage." (PMID 41208889, 2025).
tumor (continued). "However, further studies to uncover additional coding/non-coding targets of METTL3, direct targets of miR-146a-5p, and upstream/downstream targets of SMAD4 responsible for its tumor-associated function in OSCC need to be probed." (PMID 40338154, 2025). "Many tumours have been connected to too much METTL3 expression." (PMID 40760453, 2025). "Moreover, lactylation-driven METTL3-mediated m6A RNA modification has been found to promote the immunosuppression of tumor-infiltrating myeloid cells." (PMID 40175350, 2025). "Furthermore, the upregulation of cancer suppressor genes through decreasing METTL3/m6A has also been shown to effectively inhibit tumor growth." (PMID 40136363, 2025). "In addition, METTL3, an RNA methyltransferase, has been described to facilitate tumour development by reducing the expression of APC (Adenomatous Polyposis Coli), a tumour suppressor gene." (PMID 40603707, 2025). "METTL3 overexpression accelerates tumor growth by activating the m6A-Hippo axis on CRB3." (PMID 40271153, 2025). "Therefore, the interaction of the miR-186/METTL3/Wnt signaling pathway plays an important role not only in the occurrence and development of HB but also in tumor prognosis and treatment outcomes." (PMID 41393242, 2025). "For instance, in colorectal cancer, METTL3/LDHA axis-induced glucose metabolism could overcome 5-FU resistance to promote tumor development." (PMID 39990672, 2025). "For example, METTL3 affects several specific lncRNAs or circRNAs (e.g., circQSOX1) and influences the expression of glycolysis-related genes, thereby increasing the resistance of tumor cells to the chemotherapeutic drug 5-FU." (PMID 40356985, 2025). "However, in contrast to control counterparts, Ythdf2/Mettl3‐KO tumour cells were notably rejected in immunocompetent mice." (PMID 39568154, 2024). "Therefore, the present study aimed to further explore the relationship between METTL3 expression and tumour cell glycolysis." (PMID 38429907, 2024). "In addition, miRNA-455-3p is also an ncRNA with tumor suppressor function which inhibits m6A modification mediated by METTL3 on its downstream target." (PMID 38075202, 2024). "In addition, METTL3 also increases the methylation levels, accelerates proliferation rates, promotes tumor growth, and reduces apoptosis of BC cells via m6A modification on Bcl-2 mRNA." (PMID 38961497, 2024). "Accumulated lactate in the TME effectively induces upregulation of METTL3 in tumor-infiltrating myeloid cells via H3K18 Kla, and Kla modification sites have also been identified in the zinc finger domain of METTL3, which is crucial for the capture of target RNA by METTL3." (PMID 39010066, 2024). "Overexpression of METTL3 restored the expression of these proteins and might have a role in promoting the vascularization of the tumor microenvironment." (PMID 38331776, 2024). "Therefore, METTL3 is considered essential for maintaining homeostasis and tumor immunosurveillance function in NK cells." (PMID 38322265, 2024). "Therefore, researchers have proposed a novel anticancer strategy to restore METTL3/FSP1-mediated ferroptosis in tumor cells." (PMID 38550378, 2024). "Moreover, The TCGA paired sample data analysis showed that the expression level of METTL3 was significantly higher in tumour tissues than in paired adjacent tissues." (PMID 38429907, 2024). "Our findings suggest that METTL3 may play a key role in tumorigenesis and progression by promoting tumour cell proliferation, migration, glycolysis and cuproptosis." (PMID 38429907, 2024). "Additionally, METTL3 inhibition was found to enhance the killing ability of human T cells in vitro, suggesting a promising role for METTL3 in human anti‐tumour immune responses." (PMID 39568154, 2024). "Interestingly, LINC00662 suppresses miRNA-186-5p, and METTL3 is also a downstream target for miRNA-186-5p and this miRNA exerts its tumor suppressor functions by silencing METTL3." (PMID 38075202, 2024).
tumor (continued). "For example, methyltransferase 3, N6-adenosine-methyltransferase complex catalytic subunit (METTL3)-mediated m6A RNA methylation promotes the homeostasis and tumor immunosurveillance function of natural killer cells by increasing the protein expression and activity of SHP-2." (PMID 38114747, 2024). "METTL3 knockdown attenuates corneal sutures‐induced lymphangiogenesis and intratumoral lymphangiogenesis initiated by subcutaneous grafts, consequently restraining corneal neovascularization, tumor growth, and tumor neovascularization in vivo." (PMID 39372388, 2024). "In addition, there have been reports indicating that the knockdown of METTL3 significantly hastened tumor progression and reduced the lifespan of animals implanted with glioblastoma stem cells." (PMID 39054967, 2024). "Additionally, clinical studies elucidating the potential applications of METTL3 in the prognosis of different tumour stages should be conducted." (PMID 38332508, 2024). "We propose that treating tumor cells with a METTL3 inhibitor to sensitize them to chemotherapeutic drugs could be an effective treatment strategy." (PMID 39528654, 2024). "Furthermore, METTL3 inhibition within tumour can increase interferon response and enhance MHC‐I exposure." (PMID 39568154, 2024). "The research and development of m6A-modified inhibitors as therapeutic targets is receiving increasing attention.Based on the multiple roles of METTL3, targeting METTL3 may offer new hope for individualized tumor treatment." (PMID 38166703, 2024). "In addition, its upregulation in xenografts resulted in a significant increase in tumour growth, which further indicated that METTL3 facilitated LUAD tumorigenesis." (PMID 39095708, 2024). "Lingling Wang suggested that high METTL3 expression status was negatively correlated with tumor immune cell infiltration, likewise, the results showed that the immune infiltrating cells in cSCC tissues were significantly reduced after METTL3 overexpression in the animal experiment of this study." (PMID 38030537, 2024). "Depleting METTL3 leads to a significant decrease in the growth, invasion potential, and 3D soft agar colony formation of cancer cells in vitro, as well as a reduction in tumor size in mouse xenografts originating from A549 lung cancer cells." (PMID 39333489, 2024). "METTL3 is involved in important processes in tumours by mediating m6A modifications." (PMID 38238831, 2024). "Tumor suppression can be achieved by downregulating METTL3 expression." (PMID 39678510, 2024). "METTL3 deficiency in TAMs downregulates m6A modification on IRAKM, which, in turn, slows down its degradation and suppresses TLR signaling-mediated TAM activation, inhibiting proinflammatory cytokine expression and promoting tumor progression." (PMID 39133578, 2024). "Finally, the potential relationship between METTL3 and tumour cell glycolysis, cuproptosis and ceRNA were studied, which is expected to provide more effective and personalized treatment options for ESCA patients." (PMID 38429907, 2024). "The results showed that METTL3 protein was expressed at lower levels in tumor tissues." (PMID 39497721, 2024). "Recent studies have discovered that stem cell markers such as doublecortin-like kinase (DCLK1) and RNA modification by methyltransferase-like 3 (METTL3) also play a role in the recruitment of CXCR2+ TANs to modulate tumor immunity through the CXCL1−CXCR2 axis in CRC mouse models." (PMID 39795864, 2024). "Moreover, inhibition of METTL3 or METTL14 expression also enhanced tumor growth upon transplantation of GSC cells into mouse brains." (PMID 38398118, 2024). "Similarly, in hepatoblastoma, SLC7A11 upregulation, driven by IGF2BP1 through METTL3-m6A modification, supports tumor proliferation and inhibits ferroptosis." (PMID 39695216, 2024).
tumor (continued). "HBXIP increases the expression of METTL3 through restraining the expression of tumor suppressor let-7g, and METTL3 in turn upregulates HBXIP via m6A modification, thus forming a positive feedback regulatory loop of HBXIP/let-7g/METTL3/HBXIP, and ultimately causing the malignant growth of BC cells." (PMID 39054967, 2024). "In summary, our findings unveil an intricate signaling network involving METTL3/FGF2/PI3K/AKT/mTOR in LUAD and provide valuable insights into the molecular mechanisms underlying tumor progression, thus holding significant implications for targeted therapy and advancing LUAD research." (PMID 39497721, 2024). "Tumor sphere assays evaluation revealed the remarkable reduction the sphere-forming ability of CD44( + )-OSCC cells following METTL3 knockdown, which could be partially reversed it by SALL4 overexpression." (PMID 38355684, 2024). "The opposing roles of METTL3 in different cancers may be related to tumor heterogeneity and METTL3 complex physiological functions, and METTL3 produces inconsistent effects in the same type of cancer." (PMID 38166703, 2024). "In addition, compared with HET metastatic tumours, Mettl3 KO also promoted pulmonary tumour metastasis with a papillary structure." (PMID 38993572, 2024). "However, the differential expression of METTL3 in various cancers and its dual regulatory effect on tumor angiogenesis suggest that we should pay attention to the development and application of METTL3 activators and inhibitors." (PMID 39691597, 2024). "Previous research has suggested that in certain cancers, METTL3 may function as a tumor suppressor gene." (PMID 38605400, 2024). "The results of m6A sequencing and RNA sequencing showed that the EC could down-regulate the expression level of FMOD in tumor tissues, which might be related to the reduction of its m6A methylation modification regulatory enzyme METTL3." (PMID 38331776, 2024). "Knocking down METTL3 in mouse models can inhibit tumor growth." (PMID 39473440, 2024). "In tumor cells, METTL3 and METTL14 can inhibit the expression of CXCL9 and CXCL10." (PMID 39726589, 2024). "Furthermore, the knockout of METTL3 in CD33+ cells attenuates MDSC differentiation and the generation of tumor-associated MDSCs in vitro." (PMID 39759516, 2024). "Ablation of METTL3 in myeloid macrophages promotes tumor growth and metastasis." (PMID 39199429, 2024). "However, the impact of METTL3-mediated m6A modification on mitochondrial fission in tumor cells remains unexplored." (PMID 38405130, 2024). "Endostar combined with cisplatin might exert anti-tumor effects by down-regulating the expression of METTL3 and FMOD." (PMID 38331776, 2024). "Downregulation of METTL3 in NK cells is highly associated with poor infiltration and function of NK cells within TME, which could accelerate tumor progression and shorten the survival of mice models with MC38 or B16-F10 syngeneic tumors." (PMID 38322265, 2024). "Another study showed that promoting the expression of METTL3 enhanced the immune surveillance of NK cells, and METTL3 knockdown inhibited the response of NK cells to interleukin-15, affected the homeostasis and tumoricidal function of NK cells, and promoted tumor growth." (PMID 39033180, 2024). "In addition, increased LA in TME upregulated METTL3 in tumor-infiltrating myeloid cells (TIMs) and enhanced Janus kinase 1(JAK1) protein translation efficiency and subsequent transcription activator 3(STAT3) phosphorylation via the m6A-YTHDF1 axis in CRC." (PMID 39033180, 2024). "Silencing of METTL3 or SND1 suppresses tumor growth and enhances Cisplatin sensitivity." (PMID 39416774, 2024). "Notably, METTL3 inhibition significantly increased the cytotoxicity of T cells towards tumour cells." (PMID 39568154, 2024). "Similarly, in HCC, inhibition of METTL3 impairs VM-related tumor vasculature formation, indicating a positive correlation between m6A levels and VM." (PMID 39098905, 2024).